PLD5P1 (PLD5 pseudogene 1)
Gene: Protein-coding gene on chromosome 10 (38,094,368 to 38,360,098, forward strand). Ensembl gene ENSG00000283930.
Genetic constraint (gnomAD): Missense variants: 84 observed, 95.52 expected, observed/expected ratio (o/e) 0.88, 90% interval 0.74 to 1.05. Synonymous variants: 35 observed, 32.83 expected, observed/expected ratio (o/e) 1.07, 90% interval 0.81 to 1.41.